ZNF529 (zinc finger protein 529)
Description:
May be involved in transcriptional regulation.
Synonyms: KIAA1615
Tractability: PROTAC: UniProt records ubiquitination sites on it; ubiquitination databases record sites on it.
Gene: Protein-coding gene on chromosome 19 (36,534,774 to 36,605,276, reverse strand). Ensembl gene ENSG00000186020.
Subcellular location: Nucleus
Subcellular location (Human Protein Atlas): Nucleoplasm
Pathways (Reactome):
Gene expression (Transcription): Generic Transcription Pathway
Gene Ontology:
Molecular function: DNA-binding transcription factor activity, RNA polymerase II-specific; RNA polymerase II transcription regulatory region sequence-specific DNA binding
Biological process: regulation of transcription by RNA polymerase II; regulation of DNA-templated transcription
Cellular component: nucleus
Genetic constraint (gnomAD): Loss-of-function variants: 10 observed, 6.49 expected, observed/expected ratio (o/e) 1.54, 90% interval 0.9 to 1.94. That is too few expected variants to judge how well the gene tolerates losing a copy. Missense variants: 589 observed, 645.55 expected, observed/expected ratio (o/e) 0.91, 90% interval 0.85 to 0.98. Synonymous variants: 193 observed, 210.91 expected, observed/expected ratio (o/e) 0.92, 90% interval 0.81 to 1.03.
Homologues: Orthologues: chimpanzee ZNF529 (99% identical), macaque ZNF529 (96% identical), dog ZNF529 (75% identical), pig ZNF529 (74% identical), Drosophila melanogaster CG3281 (24% identical), Drosophila melanogaster Phs (21% identical), Drosophila melanogaster CG2712 (19% identical). Paralogues in human: ZNF404 (44% identical), ZNF582 (42% identical), ZFP37 (37% identical), ZFP90 (37% identical), ZNF264 (37% identical), ZNF266 (37% identical), ZNF805 (37% identical), ZNF599 (36% identical), ZNF566 (36% identical), ZNF555 (36% identical), ZNF248 (35% identical), ZNF25 (35% identical), and 50 more.
Diseases named in the same sentence as ZNF529 in open-access papers:
ZNF529 is named in the same sentence as 5 diseases in open-access papers, as found by Europe PMC text mining. Sharing a sentence is not in itself a finding about the gene and the disease. The quoted sentences say what the papers report.
diabetes (1 paper, 2022). "We also found an elderly individual with homozygous ZNF529 loss-of-function variant showing no signs of cardiovascular disease or diabetes, suggesting that the full knockout of this gene is viable." (PMID 36777998, 2022).
dyslipidemia (1 paper, 2020). "This suggests that inhibition of ZNF529 or its gene product should be prioritized as a novel candidate drug target for treating dyslipidemia and associated CVD." (PMID 33339817, 2020).
hepatoma (1 paper, 2020). "Silencing of ZNF529 in human hepatoma cells results in upregulation of LDL receptor and increased LDL uptake in the cells." (PMID 33339817, 2020). "To experimentally assess the consequence of ZNF529 LoF on cholesterol metabolism, we transiently knocked-down ZNF529 in human hepatoma HepG2 cells using siRNA (90.1% reduction, P = 2.7 × 10−8) and conducted an unbiased analysis of gene expression using RNA sequencing." (PMID 33339817, 2020).
ZNF529 also shares sentences with these, for which no sentence is quoted: cardiovascular disease (1 paper); leukoplakia (1).